RASAL2-AS1 (RASAL2 antisense RNA 1)
Gene: Long non-coding RNA gene on chromosome 1 (178,090,677 to 178,094,444, reverse strand). Ensembl gene ENSG00000224687.
Subcellular location: Membrane